MMP3 (matrix metallopeptidase 3)
Diseases named in the same sentence as MMP3 in open-access papers (continued):
Sharing a sentence is not in itself a finding about the gene and the disease.
tumor (continued). "BB94 is a potent extracellular broad-spectrum MMP inhibitor that inhibits MMP-1, MMP-2, MMP-3, MMP-7, and MMP-9 and distant tumor metastases." (PMID 35440570, 2022). "These reported significantly higher concentrations of mainly MMP-1, MMP-2, MMP-3 and MMP-9, but also of other MMPs in the saliva of patients with OSCC, compared to healthy controls, which were also correlated with the tumor stage." (PMID 36547091, 2022). "MMP3 is a member of the MMP family, and alterations to MMPs in vivo play crucial roles in promoting tumor invasion and metastasis." (PMID 35400271, 2022). "This decrease in stromal CAVIN1 contributes to the upregulation of inflammatory signatures, like increased matrix metalloproteinase-3 (MMP3), dickkopf-1 (DKK1), and CSF-1 secretion, thus attracting macrophages for a tumor-supportive microenvironment." (PMID 36117852, 2022). "The IL-6 target genes MET, IGF1, MMP3, CEACAM1, MMP1 and WNT5A were upregulated, which enabled the tumour cells to become invasive." (PMID 35022523, 2022). "In MDA‐MB‐231, we found a significant upregulation of LAPTM4B, RAB40C, MMP3, and downregulation of PRKCZ after tumor treatment with doxorubicin." (PMID 34109737, 2022). "Complementary to that, MMP3 was differentially upregulated in MB-KO cells, indicating active ECM degradation, which is an important step during tumor metastasis." (PMID 36232784, 2022). "Meanwhile, Mmp3, Mmp9, Mmp16 and Mmp10, which belong to the MMP family and are closely related to tumor metastasis, were downregulated." (PMID 35296801, 2022). "A total of six upregulated genes (FN1, APOA1, CXCL8, MMP1, MMP3, and THBS1) in tumor tissue were identified by the differential analysis of 10 hub genes." (PMID 35719376, 2022). "MMP-1 and MMP-3 had significantly higher salivary levels in OSCC, correlated with tumor stage, compared to the nearly undetectable levels in the saliva of control subjects." (PMID 36547091, 2022). "In BCC's stroma and the peritumoral area, CAFs can secrete an array of MMPs (e.g., MMP-1, MMP-2, MMP-3, MMP-9, MMP-11, MMP-13, MMP-14, MMP-19), all of them promoting ECM remodeling and favoring tumor escape from the anti-tumoral action of the immune cells." (PMID 35572966, 2022). "MMP-3 promotes the transcription of the connective tissue growth factor (CTGF) gene, involved in cell migration and tumor growth, by interacting with heterochromatin protein gamma." (PMID 34204372, 2021). "The protein concentrations of MMP-1, MMP-2, MMP-3, and MMP-9 also have been seen to be greater in OSCC tumor tissue in contrast to control tissue." (PMID 33892690, 2021). "We found that MMP1, MMP3, MMP7, MMP9-MMP12, and MMP14 were significantly upregulated in tumor tissue, while MMP15–MMP17, MMP19–MMP21, MMP23A, MMP23B, and MMP25–MMP28 were significantly downregulated in tumor tissue." (PMID 34804973, 2021). "Several metalloproteinases such as MMP2, MMP3, MMP9 and MT1-MMP have been shown to be upregulated in lymph nodes or lung tissues distant from the primary tumor by tumor-derived exosomes." (PMID 33809973, 2021). "MMP1, MMP3, MMP7, MMP12, and MMP13 belong to the matrix metalloproteinase family, and MMPs were able to participate in the tumor metastasis process by degrading the ECM." (PMID 34381520, 2021). "Analysis showed that MMP3 and SLC2A1 expression were significantly higher in OSA tissue compared to non-tumor tissue and protein expression in OSA was confirmed by immunohistochemistry." (PMID 34414229, 2021). "For example, pre-metastatic factors such as Ang2, MMP3 and MMP10, which are upregulated in the pre-metastatic lungs by primary tumours, can disrupt the vascular integrity synergistically to facilitate the extravasation of tumour cells." (PMID 35006432, 2021). "Thereafter, western blot was performed to quantify the expression levels of matrix metalloproteinases (MMP)-3 and MMP-9, which were involved in tumor invasion and metastasis." (PMID 33371778, 2021).
tumor (continued). "Consistent with the results of previous in vitro studies, IHC staining of tumor sections showed higher levels of GBP5, p-Src, p-ERK1/2, and MMP3 in U87-GBP5 tumors relative to the control tumors." (PMID 33608513, 2021). "MMP1, MMP3, and MMP1 can break down extracellular matrices and potentially contribute to tumor invasion." (PMID 33606788, 2021). "Based on the TCGA and GTEx data, we found that MMP1, MMP3, MMP7, MMP9, MMP12, MMP13 all increased in the tumor as compared with the normal esophageal tissues." (PMID 34559117, 2021). "The study also showed important differences in the levels of mRNA and protein overexpression of MMP-1, MMP-3 and MMP-9 in the tumor tissue compared to normal skin." (PMID 34204372, 2021). "In human OSA, MMP3 is highly expressed in OSA tissue in comparison with normal bone, and has been shown to be regulated by tumor suppressing microRNAs which are down-regulated in OSA." (PMID 34414229, 2021). "In the furthermore bioinformatics analysis, we found that MMP1, MMP3, MMP7, MMP9, MMP12, MMP13 all increased in the tumor as compared with the normal esophageal tissues." (PMID 34559117, 2021). "We found that, the transcriptional level of MMP1, MMP3, MMP7, MMP9–MMP12, and MMP14 in tumor were significantly upregulated, both in public database and in our samples." (PMID 34804973, 2021). "As expected, Western blot analysis of these tumor tissues showed that overexpression of GBP5 increased the levels of p-Src, p-ERK1/2, and MMP3." (PMID 33608513, 2021). "Among the MMPs family, MMP3, which also known as Stromelysin 1, is secreted robustly by activated fibroblasts and cleaves E-cadherin, thus prompting the process of EMT and invasiveness in surrounding tumor cells." (PMID 34953503, 2021). "We observed also MMP-3 immunoreactivity in both tumor cells and stromal cells whereas previous studies have shown stronger MMP-3 expression in tumor cells than in stromal cells in ADC." (PMID 33905434, 2021). "The mechanism of action is that the number of apoptotic bodies and the expression levels of GPR124, MMP-3, and VEGF increase in tumor tissues." (PMID 34641334, 2021). "In this study, we found that compared with the tumor group alone, the NK-exosome-treated tumor group exhibited a significant decrease in the expression of CD133, Bmi-1, MMP-3, IL-1β, IL-6, and TNF-α." (PMID 34527741, 2021). "The expression levels of CXCL10, IGF1, MMP3, MMP1, ICAM1, and IL-13 were significantly up-regulated in tumor tissues." (PMID 34544905, 2021). "By contrast, the NK-exosome-treated tumor group exhibited a significant reduction in Bmi-1, MMP-3, IL-1β, IL-6, TNF-α, Bax, Bcl-xL, and PCNA expression compared with that in the tumor group." (PMID 34527741, 2021). "MMP-3 can activate other MMPs, such as MMP-1, MMP-7, and MMP-9, to promote the progression of tumor initiation." (PMID 34944846, 2021). "Silencing LINC00963 inhibited the activity, proliferation, migration, and invasion of CRC cells, MMP-3 and MMP-9 expressions, moreover, it also blocked cell cycle progression, and inhibited tumor growth and Ki67 expression." (PMID 33536018, 2021). "The results revealed significant changes including the increased expression of tumorigenesis-related markers, such as CD133, Bmi-1, VEGF, MMP-3, IL-1β, IL-6, TNF-α, and MDR, as well as the apoptotic markers, Bax and Bcl-xL, in the REM134-driven tumor group." (PMID 34527741, 2021). "Our study reveals significantly reduced TWEAK in tumor samples, which is negatively correlated in tumor tissues with MMP1 and MMP3." (PMID 33846436, 2021). "All six proteins are differentially expressed in malignant vs. healthy tissue in CRC (FBLN1, MMP3, ACTN4, THBS1, EDIL3) or other tumour entities (QSOX1)." (PMID 33802764, 2021). "The present study showed the activity of MMP-3 and MMP-10 in both low-grade and high-grade tumor cells." (PMID 34441979, 2021).
tumor (continued). "We observed significant changes in tumorigenesis-related markers including CD133, Bmi-1, VEGF, MMP-3, IL-1β, IL-6, TNF-α, and MDR in the tumor group compared with the control group." (PMID 34527741, 2021). "We found that MMP1, MMP3, MMP7, MMP9–MMP12, and MMP14 were significantly upregulated in tumor tissue, while MMP28 was significantly downregulated in tumor tissue." (PMID 34804973, 2021). "There is considerable accumulating evidence suggesting a role of MMP-2, MMP-3, MMP-9 in promoting tumor cell invasion and infiltration." (PMID 33281914, 2020). "Among all MMPs, MMP-1, MMP-2, MMP-3, MMP-7, and MMP-9 are involved in almost all stages of tumor growth, angiogenesis, and metastasis." (PMID 32685465, 2020). "The results presented in the current study thus appear to contradict these earlier findings, with both MMP3 and DKK3 expressed more highly in tumor compared to non-tumor tissue." (PMID 32854182, 2020). "Among them, the expressions of MMP1, MMP3, and MMP10 in tumor tissues were higher than those in normal tissues (p < 0.05)." (PMID 32636440, 2020). "These proteases, including MMP-3, MT1-MMP (MMP-14), cathepsin B and cathepsin D, have been reported to play important roles in cancer invasion, in vivo tumor growth and distant metastasis." (PMID 33110168, 2020). "The training group was divided into four subgroups (ANO1−/MMP3−, ANO1+/MMP3−, ANO1−/MMP3+, and ANO1+/MMP3+) based on the expression status of ANO1 and MMP3 in ESCC tumor tissues." (PMID 31793228, 2020). "To further determine the mechanism of activated fibroblasts on tumor invasion, we performed qRT-PCR to detect the expression levels of five genes (ICAM-1, VEGF-C, MMP2, MMP3, and MMP9) that were reported to be involved in ESCC invasion." (PMID 32637576, 2020). "For example, VEGF, PLGF, MMP‐10, MMP‐3, Angpt2, and PTHLH released from tumor cells in various types of tumors are capable of triggering pulmonary endothelium hyper‐permeability, thereby accelerating extravasation of tumor cells." (PMID 33252861, 2020). "It has been shown that MMP3 and CCN2 (aka connective tissue growth factor (CTGF)) are often increased in tumor–stroma tissues or patients’ serum, and are thus biomarkers correlated with poor prognosis in cancer." (PMID 32260433, 2020). "The RNA interference (RNAi)-mediated knockdown of MMP3 and/or MMP9 significantly attenuated tumor growth and metastasis in the tumor allograft mouse model." (PMID 32429403, 2020). "Three variables were negatively associated with this Dim and reflected tissue remodelling (IAT MMP2 (r2 = −0.6283, p = 0.0287), tumour MMP2 and MMP3 (r2 = 60.6606, p = 0.0194; r2 = −0.6790, p = 0.0152 respectively))." (PMID 32472095, 2020). "Several studies have indicated an important role of MMP-3 and MMP-10 in the stimulation of tumor growth, metastasis, and angiogenesis in BC." (PMID 33371324, 2020). "RNA interference (RNAi) targeting MMP3 and/or MMP9 significantly lowered tumor growth and metastasis in the allograft mouse model." (PMID 32260433, 2020). "Three genes were selected, namely, ANO1, GAL, and MMP3, which were aberrantly expressed in ESCC tumor tissues (P < .001)." (PMID 31793228, 2020). "It has been also shown that MMP3 and CCN2/CTGF promote tumor progression through processes including rapid metastasis and tumor–stroma interactions." (PMID 32260433, 2020). "Significant correlations were found between MMP‐3 and TIMP‐4 levels, and some of the variables studied related to patient characteristics and tumour biology." (PMID 31568637, 2020). "To investigate the clinical significance of MMP3 and CCN2/CTGF gene expression, we searched the TCGA database of patient-derived tumor samples." (PMID 32260433, 2020). "Surprisingly, reverse transcription-PCR (RT-PCR) results showed that M/Ms from metastatic brains expressed both MMP3 and MMP9, whereas RFP-B16 tumor cells barely expressed MMP3 but produced low levels of MMP9." (PMID 30616691, 2019).
tumor (continued). "Our work revealed that MMP-3 and MMP-25 high expression levels were correlated with higher OSC tumor stage, providing further evidence of these MMPs in OSC progression." (PMID 31406154, 2019). "IL-1β was previously shown to promote tumour cell invasion and metastasis by modulating the expression of matrix metalloproteinases in cancer cells, specifically MMP1, MMP3, and MMP1045." (PMID 31558756, 2019). "MMP-3 or MMP-7 overexpression in the mammary epithelium generates premalignant lesions and spontaneous tumor formation." (PMID 31075939, 2019). "In previous studies of brain metastasis of breast and lung cancer, tumor cells were identified as the main destroyers of the blood brain barrier (BBB) via the production of MMPs (MMP1, MMP2, MMP3, and MMP9)." (PMID 30616691, 2019). "In some tumor types, TNF-α was shown to promote tumor cell migration and metastasis by inducing RAS or c-MYC activation and expression of MMPs (e.g. MMP-3 and 9)." (PMID 31600735, 2019). "In an in vivo tumour model, it was shown that that the protein, mRNA expression and/or activity of MMP-2, MMP-3, MMP-7 and MMP-9 were significantly higher in UVB-exposed skin and tumours of IL-12 knockout mice compared with wild-type mice." (PMID 29555826, 2018). "The increased CCL2 promoted an influx of CD11b+ monocytes into the primary tumor that also had increased matrix metalloproteinase (MMP)-2, MMP-3, and MMP-9 expression." (PMID 30458886, 2018). "Our data show significantly upregulated levels of MMP-1, MMP2, MMP3 and MMP9 mRNA in ESCC tumor tissues compared to the adjacent normal tissues." (PMID 30241395, 2018). "The higher expression levels of D6 sequesters available pro-inflammatory chemokines from the a2V-KO TME making it less inflammatory, while higher expression of MMP3 and CXCL7 help tumor cells to degrade extracellular matrix and metastasize." (PMID 30237863, 2018). "It is supposed that the 5A/6A polymorphism may be associated with the MMP3 gene promoter activity under interleukin and tumor necrosis factor α (TNF α) stimulation and it may influence the transcription of the gene through the regulation by cytokines released by tumor cells." (PMID 30381735, 2018). "MMP3, a member of the matrix metalloproteinase protein family, is involved in wound healing and degradation of the ECM during tissue remodelling and tumour metastasis." (PMID 29674723, 2018). "In summary, MMP3 protein is enriched in 3T3-A-EXO and can be transferred into 3LL tumor cells by exosome and cell fusion." (PMID 29137230, 2017). "After transfer, MMP3 exhibited a robust ability to activate MMP9 and promote tumor metastasis in vivo." (PMID 29137230, 2017). "Together, these data indicate both MMP3 and MMP9 are involved in the 3T3-A-EXO-mediated increase in 3LL tumor cell metastasis in vivo." (PMID 29137230, 2017). "MMP-3 and MMP-9 originating from the tumor microenvironment, tumor cells, and stromal cells adjacent to the tumor cells help to facilitate EMT via invasion and metastasis behaviors." (PMID 26828526, 2016). "Moreover, MMP-3 may activate the expression of MMP-9 in tumor cells." (PMID 26510742, 2016). "In support of an anti-tumor role for MMPs, treatment with the MMP inhibitor tanomastat, which has selective activity against MMP2, MMP3 and MMP9, was shown to lead to a worse outcome compared to standard treatments." (PMID 26956475, 2016). "MMPs were reported to induce tumor progression in HCC including MMP-1, MMP-2, MMP-3, MMP-7, MMP-9, MMP-11 and MMP-13." (PMID 26882566, 2016). "MMP-3 has been recognized as one of the major proteases responsible for ECM turnover and cell–cell interactions, as well as tumor metastasis." (PMID 26850593, 2016). "Of note, tumor-induced MDSC are enriched for multiple ecto-proteases including ADAM28, ADAM9, collagenase-3 (MMP13), stromelysin (MMP3), macrophage elastase, and leukocyte elastase." (PMID 27929373, 2016).
tumor (continued). "One well-known substrate for MMP3 is pro-MMP9, which has been reported to be a potent mediator of tumor progression." (PMID 26008967, 2015). "Third, we found that DSF effectively inhibited tumor cell migration and invasion through modulation of MMP-1 and MMP-3 expression." (PMID 26517513, 2015). "It inhibits MMP-2, MMP-3, TIMP-1, and TIMP-3 in preventing tumor angiogenesis, and MMP-9 through an autocrine loop in blocking lung and liver metastasis mediated by stromal fibroblasts." (PMID 25909283, 2015). "MMPs secreted by stromal cells, especiallyMMP-2, MMP-3 and MMP-9, contribute equally or even more to tumor cell invasion than MMPs secreted from cancer cells." (PMID 25629807, 2015). "To extend our preliminary observations from the gene expression data, we examined MMP3 expression at multiple molecular and biochemical levels, first in the same CMS4 tumor model." (PMID 26008967, 2015). "Its role as a promoter of tumorigenesis, anchorage-independent growth and cell invasion stems from evidence that it targets the PTEN tumor suppressor, TPM1 and Matrix Metalloproteinase 3 (MMP3)." (PMID 29861413, 2015). "The invasiveness occurred through MMP2 and MMP3, while inhibition of VEGFA decreased the tumor growth." (PMID 26308848, 2015). "Since MMP1, MMP3 and MMP9 were involved in tumor invasion and metastasis and can be regulated by NF-κB pathway, we further investigated the effect of RANKL on the MMPs." (PMID 25268581, 2014). "It has been previously shown for tumor cells that AMF-induced motility is mediated by upregulation of MMP2 and MMP3." (PMID 24736611, 2014). "EMMPRIN proteins have been well documented to stimulate the synthesis of MMPs such as MMP-1, MMP-2, MMP-3, and MMP-9 in fibroblast and tumor cells." (PMID 24705283, 2014). "In Dittmer study reported that over-expression of ETS1 would promote tumor invasion due to its ability to activate the MMP1, MMP3, MMP9 and uPA as well as of VEGF in tumorigenesis." (PMID 23405089, 2013). "CD204(+) macrophages reportedly exhibit a tumor-promoting function in several tumors by secreting matrix metalloproteinase (MMP)-1, MMP-3, MMP-7, MMP-9, MMP-12, vascular endothelial growth factor (VEGF), and transforming growth factor (TGF)-β." (PMID 24376714, 2013). "Among the seven MMPs tested, both MMP-3 and MMP-9 were elevated in samples from the tumor site when compared with that from the adjacent normal tissues." (PMID 22873525, 2012). "We have previously reported that mRNAs for several MMPs, including Mmp2, Mmp3, Mmp11 and Mmp14 are expressed in the MMTV-PyMT tumor stroma." (PMID 18698413, 2008). "These leukocytes produce cytokines, and growth and angiogenic factors, as well as matrix-degrading proteases (such as the matrix metalloproteinases MMP1, MMP3 and MMP9) and their inhibitors, which allow tumour cells to proliferate, invade and metastasise." (PMID 19050705, 2008). "The data demonstrated an incremental increase in tumor cell invasion with increasing concentration of MMP-3, with a doubling of invasion in the presence of 100 ng/mL MMP-3 compared with control (p = 0.014)." (PMID 17922906, 2007). "This study has shown that tumor-derived fibroblasts exhibit higher levels of IPC than normal fibroblasts and that the MMP-3 5A/5A genotype contributes to this through enhanced MMP-3 release." (PMID 17922906, 2007). "In the mesenteric metastasis, the MDA-MB-231 tumour cells showed a moderate expression of both MT1-MMP and MMP-1 (2+), and low expression of MMP-3 (1+)." (PMID 16430785, 2006). "Using quantitative RT–PCR, overexpression of MMP1, MMP3, MMP7, MMP11, MMP12 and MMP13 in desmoid tumours was demonstrated." (PMID 15054469, 2004). "Expression of MMP-10 was compared with that of stromelysin-1 (MMP-3) and of MT1-MMP, the expression of which has been shown to correlate with tumour invasiveness." (PMID 11237387, 2001).